ISG15 (ISG15 ubiquitin like modifier)
Diseases named in the same sentence as ISG15 in open-access papers (continued):
Sharing a sentence is not in itself a finding about the gene and the disease.
viral infection (continued). "In order to characterize if different ISG15 deficient cell types exhibit variable susceptibility to viral infection, we examined VACV replication in different primary cells, derived from both ISG15+/+ and ISG15−/− mice." (PMID 24137104, 2013). "ISG15 is a critical molecule for the response against several viral infections since ISG15−/− mice are more sensitive to influenza A and influenza B viral infections and also show an increased susceptibility to murine herpes virus and to Sindbis virus." (PMID 22693631, 2012). "UbcH8 and UbcH6 are ISG15-conjugating E2 enzymes that are induced by type I IFNs and viral infection." (PMID 23109884, 2012). "We showed that although the IFNβ gene is stochastically expressed upon virus infection, the antiviral ISGs, e.g., ISG15, were equally induced in all cells." (PMID 22291574, 2012). "Secondly, it is not alone but with a good prototype in Japanese flounder, which demonstrates that mRNA levels of IFN-I and ISGs (Mx and ISG15) in the hirame natural embryo cells overexpressing LGP2 are increased by viral infection." (PMID 22860079, 2012). "ISG15 has characteristics pointing to its vital role in the innate immune response to viral infections." (PMID 23109884, 2012). "Several studies now demonstrate that intracellular free ISG15 and conjugated ISG15 play an important role in innate immunity against viral infection, suggesting a crucial role of ISG15 in well-established immunological effects of interferon." (PMID 21298066, 2011). "To date, the ability of ISG15 to protect against viral infection has been shown to be dependent on its ability to covalently bind (or conjugate) to target proteins, including the binding of viral proteins." (PMID 22028657, 2011). "Further support for the importance of ISG15 conjugation during viral infection comes from the evolution of viral proteins that directly target ISG15 conjugate formation." (PMID 22028657, 2011). "The ubiquitin-like molecule ISG15 has been shown to play an important role during multiple viral infections, including influenza virus infection." (PMID 22028657, 2011). "The expression of ISG15 can be induced by type I interferons (IFNs), viral infections and LPS, suggesting that ISG15 is a broad spectrum of stress response gene." (PMID 21992229, 2011). "We had previously shown that the conjugation of ISG15 to target proteins is essential for the control of several viral infections." (PMID 22028657, 2011). "ISG15 is an ubiquitin-like protein rapidly induced in response to virus infection and IFN treatment." (PMID 21533103, 2011). "Since ISG15 plays distinct role in different viral infection model, we use DENV and WNV to explore the function of ISG15 in these two vector-borne RNA viruses." (PMID 21992229, 2011). "It would also provide additional support for ISG15 playing a significant role during viral infection." (PMID 21994614, 2010). "While both free ISG15 and ISG15 conjugates were detected during viral infection, ISGylation was shown to be required for ISG15-dependent resistance to Sindbis and influenza virus in vivo." (PMID 21994614, 2010). "Significant progress has been made in identifying the components of the ISG15 conjugation cascade, understanding how these proteins are induced during viral infection, and identifying potential targets for ISGylation." (PMID 21994614, 2010). "Interferon stimulated gene (ISG)-15 is a type I interferon-induced molecule that is rapidly upregulated in response to viral infection." (PMID 18851747, 2008). "ISG15 expression is almost undetectable under normal conditions but is strongly up-regulated during viral infections such as human cytomegalovirus (HCMV), herpes simplex virus (HSV), Sindbis virus (SV) and hepatitis C virus (HCV)." (PMID 18604270, 2008). "In mice and cells deficient in type I IFN receptor R1 (IFNR1), ISG15 production decreases significantly following treatment with lipopolysaccharide (LPS) from Gram-negative bacteria or viral infections." (PMID 40284971, 2025).
viral infection (continued). "In addition to its intracellular functions, recent studies have revealed a novel role for extracellular ISG15, particularly in the context of viral infections." (PMID 40719862, 2025). "Recent studies have investigated ISG15 secretion pathway in the context of viral infection." (PMID 40719862, 2025). "Among these genes, ISG15, an interferon-stimulated gene induced by type I interferons during viral infection, was significantly upregulated across multiple brain lymphocyte clusters, including tissue-resident memory (TRM), γδ T cells, proliferating T cells, and EM clusters (Fig. 5Eand Suppl." (PMID 40386405, 2025). "Importantly, numerous studies have found that ISG15 can also be released by cells, particularly during viral infection, yet much less is known about the function of this “extracellular ISG15”." (PMID 40719862, 2025). "The increase in OAS2 and MX1 once again underscores a shared antiviral strategy across different viral infections, and ISG15 (interferon-stimulated gene 15) points to a broader modulation of the immune response, given its role in protein ubiquitination related to antiviral defense." (PMID 38655085, 2024). "There were a few overlapped genes among the different DEG lists, and the only common upregulated DEG shared by the three circumstances was ISG15, which encodes a ubiquitin-like protein, activated by type I IFN and functioning in the innate immune response to viral infections." (PMID 38675895, 2024). "A greater number of genes are upregulated in DCs after MRV infection, many of which are involved in the innate immune response (i.e. Ifit1, Ifit3, Mx1, Gbp2, Oasl1, Isg15, Ccr1, Ifitm2, Oaxl2, Casp1, Casp4) that would be predicted in response to a viral infection." (PMID 38895117, 2024). "Isg15 is a ubiquitin-like protein that is particularly strongly induced in viral infections." (PMID 39772143, 2024). "The HERC5 and ISG15 pathways are established regulators of antiviral immune response among viral infections including SARS-CoV-2 and HIV and may expand to CCHFV as well." (PMID 39599842, 2024). "Under-expression of MX1, ISG15, RSAD2, IFIT1, and OAS2 may weaken the ability of the immune system to effectively counter viral infections, leaving the heart tissues susceptible to viral invasion and potentially contributing to MMVD progression." (PMID 38753730, 2024). "Surprisingly, humans with ISG15 deficiency do not show increased susceptibility to viral infection, possibly due to concomitant reduction of USP18 expression and USP18-dependent negative regulation of IFN-dependent signaling." (PMID 37025175, 2023). "The results will be useful for our understanding of the ISG15 function during viral infection and may contribute to exploring novel candidates for anti-BTV infection." (PMID 37637123, 2023). "Human patients with recessive inheritance ISG15 deficiency (ISG15−/−) do not appear to be more susceptible to viral infection." (PMID 37298304, 2023). "Most evidence for a role of ISG15 in CVD is related to viral infection." (PMID 37025175, 2023). "Furthermore, viral infection increased the mRNA expression of cytokines (Il6, Tnf), chemokines (Cxcl10, Ccl2), and interferon-responsive genes (Ifnb1, Ifit3, Irf7, Gbp5 and Isg15)." (PMID 37081549, 2023). "In vitro, IFN-β and ISG15 directly confers resistance to viral infections." (PMID 36949543, 2023). "Moreover, ISG15 suppresses viral infection in human cardiomyocytes, and patients with viral cardiomyopathy show conjugated ISG15 induction in the myocardium." (PMID 37025175, 2023). "ISG15 directly inhibited virus infection through ubiquitin-like viral proteins." (PMID 37256060, 2023). "These functional roles for free ISG15 were uncovered while studying ISG15 deficient patients, who interestingly displayed a lack of viral disease, but increased susceptibility to mycobacterial disease and an enhanced type-I interferon response." (PMID 38042859, 2023).
viral infection (continued). "PPRV infection can stimulate high levels of interferon (IFN) and many IFN-stimulated genes (ISGs), such as ISG15, which may play a key role in the process of viral infection." (PMID 36036587, 2022). "In addition, ISG15 is one of the immediate-early genes induced by viral infections independently of type I IFNs and its roles in defense against viruses at an early stage are not fully understood." (PMID 36217001, 2022). "ISG15 is promptly upregulated by viral infection and type I IFNs30." (PMID 36217001, 2022). "In vitro studies in mouse cells have demonstrated an antiviral role of ISG15 during several viral infections, although there are some reports of viruses displaying no enhanced replication when ISG15 is deficient." (PMID 36146669, 2022). "Microglia are already known to induce CXCL10 and ISG15 expression during viral infection." (PMID 36680128, 2022). "The upregulation of Isg15 (and other interferon-stimulated genes) has been linked not only to viral infection but also to DNA damage." (PMID 35246516, 2022). "Consistent with the quantitative proteomic results, qRT‐PCR results showed that along with a lower level of viral titration, higher levels of ISGs such as Isg15, Oasl2, and Stat1 were detected in livers of WT mice than those from Neurl3−/− mice post‐viral infection." (PMID 35792897, 2022). "In the present study, the transcription levels of IFN-β, OAS1, Mx1, and ISG15 in the lungs and intestines of mice pretreated with L. plantarum 0111 were correspondingly increased, and the lung viral load was significantly reduced after viral infection." (PMID 35847111, 2022). "SARS-CoV-2 Plpro antagonistic activity against ISG-15 might block the production of various cytokines involved in the activation of the innate immune response against viral infection, e.g., Type I IFN-β and chemokines such as CXCL10 and CCL5." (PMID 35891385, 2022). "Further studies on Lates ISG15 in other viral infections will provide a deeper insight into innate immune antiviral mechanisms in Lates calcarifer, which may lead to the development of new prophylactic strategies and immunological tools to improve fish health." (PMID 36419602, 2022). "In vitro, IFN-β and ISG15 can directly resist viral infections, whereas pro-inflammation cytokines IL-6 and IL-8 may not have antiviral effects on a single cell." (PMID 35418961, 2022). "Moreover, ISG15 regulates tissue damage and/or repair responses, specifically in the context of viral infection of the respiratory epithelium." (PMID 35365634, 2022). "Patients with ISG15 deficiency do not have an increased risk of viral infections, and ISG15–/– cells are less susceptible to certain viral infections, possibly due to the persistently elevated IFN levels." (PMID 35842904, 2022). "Peritoneal macrophages from ISG15-deficient mice too were unable to phagocytose infected cells nor block virus infection in co-cultures with infected fibroblasts." (PMID 36416643, 2022). "Therefore, understanding how ISG15 influences cellular function during a viral infection is essential to clarifying the diverse range of biochemical outcomes that can occur as a consequence of host ISGylation activity." (PMID 34207696, 2021). "Additionally, ISG15 plays various roles in the defence against viral infections and the activation of immune system cells such as lymphocytes, monocytes, and natural killer cells." (PMID 34650121, 2021). "Consistent with results obtained from the virus-infected HINAE cells, until 6 h after viral infection, the expression of ISG15 and Mx was down-regulated in the kidney, spleen, and liver of rVHSV-P-infected fish, whereas their expression was up-regulated in rVHSV-wild-infected fish." (PMID 33465148, 2021). "Moreover, ISG15 is a ubiquitin-like protein which plays a key role in the innate immune response to viral infection via its conjugation to a target protein (ISGylation)." (PMID 34267761, 2021).
viral infection (continued). "During viral infections, including COVID-19, one of the most rapidly induced interferon related genes is ISG-15, which has been shown to inhibit viral replication, impede the externalization and latency of virions and, as an extracellular protein, functions as a chemotactic cytokine for neutrophils." (PMID 34685525, 2021). "Contrary to expectations, no particular susceptibility to viral infections was observed in these ISG15-deficient patients." (PMID 33424843, 2020). "This has implications for our understanding as to why ISG15-deficient patients are not more susceptible to viral infections; these observations have led to the suggestion that, unlike in mice, human ISG15 is not an antiviral effector." (PMID 32423918, 2020). "ISG15 plays a central role in the host defense to viral infections." (PMID 32736569, 2020). "The related proteins revealed are MAVS (520 aa), ISG15 (a ubiquitin-like protein that has an essential role in the innate immune response to viral infection either via its conjugation to a target protein, ISGylation, or via its action as a free or unconjugated protein)." (PMID 33488570, 2020). "Furthermore, whereas infection of IFN-α–pretreated ISG15-knockout cells significantly reduced infection compared with control cells, virus infection in these cells was still more robust compared with PIV5 and HPIV2-infected cells." (PMID 32423918, 2020). "ISG15 is largely stimulated during antiviral responses, and although its broad functions are not fully elucidated, it acts as an effector and a regulator of the host cells innate immune response during viral infections." (PMID 32429099, 2020). "In mice, ISG15 plays an important role in host response to viral infection." (PMID 32039148, 2019). "This role for ISG15, which is absent in mice, seems to be predominant in humans, since patients appear not to be more susceptible to viral infections." (PMID 30428561, 2018). "The situation is complicated by the fact that in some situations, for example viral infection, loss of histone acetylation is linked to increased, rather than decreased, ISG15 levels." (PMID 29787576, 2018). "Many ISG15-conjugated proteins control cellular responses to viral infection, IFN, and DNA damage." (PMID 29367604, 2018). "Interferon-stimulated gene 15 (ISG15) plays an important antiviral role during viral infection." (PMID 30428561, 2018). "The results of immunoblot analysis showed that IE1 overexpression suppressed the induction of ISG15 and ISG15 conjugates by both virus infection and IFNβ treatment (as a control) (compare lanes 2–5 and 7–10), further supporting the critical role of IE1 in reducing ISG15 expression." (PMID 27564865, 2016). "Our results demonstrate that ISGylation inhibits HCMV growth at multiple steps and that HCMV has evolved countermeasures to suppress ISG15 transcription and protein ISGylation, highlighting the importance of the interplay between virus and ISGylation in productive viral infection." (PMID 27564865, 2016). "ISG15 plays also a role in the response to many viral infections." (PMID 27626177, 2016). "In mice, ISG15 has been shown to have a protective role in response to a variety of virus infections, although the precise mechanism remains unknown." (PMID 27357150, 2016). "Accordingly, we used ISG15-deficient fibroblasts transduced with ISG15ΔGG, which exhibit fully functional downregulation of IFN signalling but no ISGylation, to determine the relative role of each function during viral infection." (PMID 27193971, 2016). "It has been suggested that newly synthesized viral proteins may be broadly modified by ISG15 during virus infection." (PMID 27564865, 2016). "In addition, dozens ISGs, among which some have been characterized for their antiviral activities against various other viral infections, for example Mx1, Ifit1, Isg15, Ifi44, Ddx60, Oasl and Irf7 were up-regulated upon HDV inoculation in hNTCP-Tg mice." (PMID 25902143, 2015).
viral infection (continued). "Though the exact outcome of PLpro's deISGylating activity during viral infection is currently unknown, ISG15 is an important activator of the immune response." (PMID 24854014, 2014). "We further investigated whether interference with inositol pyrophosphate-synthesis-pathway kinases can affect viral infection dependent induction of ISG15 (a major interferon stimulated antiviral gene) in Sendai virus challenged HEK293 cells." (PMID 24586175, 2014). "HOIP has also been shown to interact with the ISG15 (interferon-induced 15 kDa protein) E3 ligase TRIM25 (tripartite motif-containing 25), an enzyme implicated in the innate immune response against viral infection, and Gumby, a linear deubiquitinase involved in modulating the Wnt signalling pathway." (PMID 24576094, 2014). "Since ISG15 responds to not only various types of IFNs but also viral infection, increase of ISG15 gene expression found in this study might attribute to viral infection." (PMID 22439976, 2012). "Our CHIKV model may provide an opportunity to identify a novel mechanism by which ISG15 contributes to the innate immune response to viral infection." (PMID 22028657, 2011). "This study provides new insight into the control of CHIKV infection, and establishes a new model for how ISG15 functions as an immunomodulatory molecule in the blunting of potentially pathologic levels of innate effector molecules during the host response to viral infection." (PMID 22028657, 2011). "The ability of ISG15 to conjugate to target proteins appears to be essential for ISG15's antiviral activity during certain viral infections, as UbE1L−/− mice, which lack the ability to form ISG15 conjugates, phenocopy ISG15−/− mice during both SINV and influenza B virus infection." (PMID 22028657, 2011). "While ISG15 may regulate a variety of cellular processes, it appears to play a critical role in the host response to viral infection." (PMID 21994614, 2010). "Together, these studies provide the first insight into one mechanism by which ISG15 may regulate viral infection, by targeting multiple stages of budding for viruses that utilize ubiquitin machinery and ESCRT pathway." (PMID 21994614, 2010). "It has been speculated that the ISG15 up-regulation following viral infection is involved in different strategies of the antiviral response." (PMID 18604270, 2008). "Moreover, although ISG15 knock-out mice were initially found to be as vulnerable to viral infections as their wild type countermates, a subsequent study discovered ISG15 knock-out mice to be more vulnerable to Influenza, Herpes and Sindbis viral infection." (PMID 18560560, 2008). "Although ISG15 conjugation is strongly induced by viral infection, UBA7-deficient mice show no significant different from controls upon infection with vesicular stomatitis and lymphocytic choriomeningitis viral infections, suggesting redundancy within interferon signaling pathways." (PMID 40570956, 2025). "However, a comprehensive understanding of ISG15’s role in viral infection remains elusive." (PMID 40284971, 2025). "Interestingly, CCCP elicited an opposite effect on host genes such as IFN-β and ISG15, both of which are involved in host defense against viral infection, suggesting that CCCP-mediated mitochondrial depolarization regulates IFN pathway as well as viral replication." (PMID 38184594, 2024). "Viral infection, however, is not the only cause of cardiomyocyte ISG15 induction." (PMID 38665231, 2024). "ISG15 was initially studied for its anti-viral property in mice; however, against expectations, inherited ISG15-deficient patients do not show increased susceptibility to viral infection." (PMID 39345209, 2024).